OR6K2 (olfactory receptor family 6 subfamily K member 2)
Description:
Odorant receptor.
Synonyms: OR1-17
Tractability: Antibody: UniProt places it where antibodies can reach, with medium confidence; UniProt predicts a signal peptide or a membrane-spanning region; its Gene Ontology location is reachable by antibodies, with medium confidence.
Gene: Protein-coding gene on chromosome 1 (158,699,678 to 158,700,652, reverse strand). Ensembl gene ENSG00000196171.
Subcellular location: Cell membrane
Pathways (Reactome):
Sensory Perception: Expression and translocation of olfactory receptors
Gene Ontology:
Molecular function: odorant binding; olfactory receptor activity; G protein-coupled receptor activity
Biological process: detection of chemical stimulus involved in sensory perception of smell; G protein-coupled receptor signaling pathway
Cellular component: membrane; plasma membrane
Genetic constraint (gnomAD): Loss-of-function variants: 8 observed, 4.92 expected, observed/expected ratio (o/e) 1.63, 90% interval 0.88 to 1.94. That is too few expected variants to judge how well the gene tolerates losing a copy. Missense variants: 450 observed, 425.36 expected, observed/expected ratio (o/e) 1.06, 90% interval 0.98 to 1.14. Synonymous variants: 139 observed, 152.48 expected, observed/expected ratio (o/e) 0.91, 90% interval 0.79 to 1.05.
Homologues: Orthologues: chimpanzee OR6K2 (96% identical), macaque OR6K2 (91% identical), rabbit OR6K2 (87% identical), mouse Or6k2 (84% identical), rat Or6k2 (84% identical). Paralogues in human: OR6K6 (59% identical), OR6K3 (59% identical), OR6N1 (50% identical), OR6N2 (49% identical), OR4S2 (39% identical), OR7C1 (38% identical), OR10R2 (38% identical), OR10Z1 (38% identical), OR4D9 (37% identical), OR4D10 (37% identical), OR10K1 (37% identical), OR10K2 (37% identical), and 116 more.